EGFR (epidermal growth factor receptor)
Diseases named in the same sentence as EGFR in open-access papers (continued):
Sharing a sentence is not in itself a finding about the gene and the disease.
glioblastoma (continued). "It has been shown that most glioblastoma patients show little or no response to therapy using EGFR inhibitors, which suggests an intrinsic resistance against these inhibitors." (PMID 31013819, 2019). "Only the patient‐derived glioblastoma BT11, BT12 and BT13 spheroids expressed high levels of EGFR." (PMID 31068339, 2019). "However, the clinical benefits of first- and second-generation EGFR tyrosine kinase inhibitors (EGFR-TKIs) are limited in NSCLC, pancreatic cancer, and glioblastoma due to drug resistance." (PMID 31614999, 2019). "Moreover, recent studies suggest that combined administration of EGFR–mTOR inhibitors represses growth and proliferation of tumor cells and suppresses the PI3K signaling pathway in glioblastoma." (PMID 31013819, 2019). "Unlike these, the mutations in SEGA-like glioblastoma occurred in the context of other genetic aberrations present in high-grade neoplasms, including in the CDKN2A/B, PIK3R1, PIK3CA and EGFR genes." (PMID 31258848, 2019). "Moreover, HGF/MET signaling can induce EGFR and HER-3 activation, leading to enhanced activation of oncogenic signaling in glioblastoma." (PMID 31221203, 2019). "Macropinocytosis may be notably triggered by epidermal growth factor receptor (EGFR) and platelet-derived growth factor receptor (PDGFR), two well-known markers for glioblastoma aggressiveness." (PMID 30909495, 2019). "To test whether nimotuzumab inhibited signaling from the EGFR-downstream kinases Akt and mTORC1, we exposed human LNT-229 glioblastoma cells to nimotuzumab or the intracellular EGFR inhibitor PD153035." (PMID 30129426, 2018). "Amplification of receptor kinases such as EGFR and PDGFRA (platelet-derived growth factor receptor alpha) are relevant to the prognosis of glioblastoma, and both may coexist in a tumor." (PMID 30374421, 2018). "Consistent with the clinical trials, our bioinformatic analysis of TCGA glioblastoma revealed that neither EGFR nor NTN4 predicts significant survival in TMZ-treated patients." (PMID 30514230, 2018). "Monoclonal antibodies (MAbs) are used for glioblastoma treatment because of their high specificity and affinity for biological targets to improve immunotherapy and for antiangiogenic action by targeting growth factor receptors such as VEGFR, EGFR, and PDGFR." (PMID 30374421, 2018). "The EGFR-targeted TRAIL fusion protein scFv425:sTRAIL simultaneously blocks EGFR-mitogenic signaling, thereby sensitizing tumor cells to apoptosis through the TRAIL-receptor signaling in the A172 glioblastoma cell line." (PMID 30486451, 2018). "In addition to these frequent abnormalities of EGFR and PDGFRA, more rarely abnormalities of another RTK, FGFR, have been described in approximately 3% of glioblastoma patients." (PMID 30279357, 2018). "This was demonstrated with experiments using EVs generated from a parental (glioblastoma) cell line that does not have EGFR amplification (GBM20/3 cells with GFP)." (PMID 29330365, 2018). "The TAT–DRBD system was used for intracranial delivery of epidermal growth factor receptor (EGFR) and AKT serine/threonine kinase 2 (Akt2) siRNAs to treat glioblastoma in mouse models and it was showed to induce a lethal RNAi responses and increased animal survival." (PMID 29385037, 2018). "Analysis of the TCGA glioblastoma dataset and the French glioma dataset gse16011, showed no variation in ARNT2 expression according to MGMT status, IDH1 mutation or EGFR amplification (not shown)." (PMID 29149419, 2018). "Based on this, a phase I clinical evaluation of EGFR-targeted, doxorubicin-loaded minicells (EGFR(V)-EDV-Dox) was performed in human patients with recurrent glioblastoma in Australia and another phase I trial # NCT02766699 is currently under progress in the USA." (PMID 30374421, 2018). "Hence, we screened a panel of cells lines representing renal cancer (CAKI‐1, CAKI‐2, ACHN), bladder cancer (UC13, T24), and glioblastoma (U87MG), for expression of SEMA3C, EGFR, MET, Plexin B1, Plexin D1, NRP1, and NRP2." (PMID 29348142, 2018).
glioblastoma (continued). "We found the total mRNA levels of EGFR and four EGFR transcripts were dramatically reduced after PTBP1 stable knockdown, which in agreement with previous study that PTBP1 stablized mRNA of EGFR by inhibiting ANXA7-mediated EGFR degradation in glioblastoma." (PMID 28404950, 2017). "Several tyrosine kinase inhibitors (TKIs) that target the EGFR have been evaluated in clinical trials for glioblastoma patients, but all have failed to meet expectations." (PMID 29152086, 2017). "Although one of the most characteristic features of glioblastoma is alterations in EGFR, therapeutically targeting EGFR is currently not efficacious likely due to heterogeneity of EGFR signaling networks and redundant alternative signaling pathway activation." (PMID 29371993, 2017). "Taken together, these findings suggest that increased EGFR signaling may increase xCT and GSH synthesis via increased Nrf2 expression, contributing to the aggressive properties of glioblastoma." (PMID 28424758, 2017). "EGFR amplification in cells having double minute chromosomes (DM) is commonly found in glioblastoma multiforme (GBM); however, how much it contributes to the current failure to treat GBM successfully is unknown." (PMID 29113349, 2017). "Concurrent amplifications of EGFR and PDGFRA have been reported in up to 5% of glioblastoma (GBM) and it remains unclear why such independent amplification events, and associated receptor overexpression, would be adaptive during glioma evolution." (PMID 28831081, 2017). "Combined use of rapalogs with epidermal growth factor receptor inhibitors in glioblastoma or lung cancer have also resulted in no survival benefit or greater toxicities respectively." (PMID 27826244, 2016). "EGFR is the most frequently amplified gene in Glioblastoma, yet neither GISTIC2 nor RAIG detects it." (PMID 27396759, 2016). "D2C7(scdsFv)-PE38KDEL was highly cytotoxic to glioblastoma cell lines expressing EGFRvIII, as well as non-glioblastoma cell lines with EGFR amplification." (PMID 27153091, 2016). "Genomic deletion of exons 2–7 through EGFR gene amplification has been widely accepted as the primary, if not exclusive, mechanism of EGFRvIII expression in glioblastoma." (PMID 25658924, 2015). "As these oncogenic events frequently occur in glioblastoma, the cooperation between CD151-α3β1 integrin complexes and EGFR detected in the current study may only reflect part of broad contributions of such complexes to the aggressiveness of such disease." (PMID 26377974, 2015). "To further characterize gene expression in the Ad-GSCs and Sp-GSCs tumor xenografts, we examined the expression of genes previously defined to be characteristic of the Classical (FGFR3, PDFA, EGFR, AKT-2 and Nestin) and Mesenchymal (CHI3L1, TRADD, NF1, RelB and CASP4) glioblastoma subtypes." (PMID 25955030, 2015). "Also, knockdown- or pharmacological agent-based attenuation of EGFR, FAK or Graf (ARHGAP26)/small GTPase-mediated pathways markedly mitigated the aggressiveness of glioblastoma cells." (PMID 26377974, 2015). "We recently showed that soluble LRIG-1 inhibits cell growth in experimental glioblastoma models irrespective of the EGFR type or expression level." (PMID 25885672, 2015). "Additionally, PKCε- and NF-κB-dependent PKM2 up-regulation is involved in EGFR-promoted glycolysis and tumorigenesis, and PKM2 expression correlates with EGFR and IKKβ activity and with the grade of glioma malignancy in human glioblastoma specimens." (PMID 24972138, 2014). "Although v-Src has not been reported in human glioblastoma, we now know that members of SFKs are effector molecules of EGFR, PDGFR, VEGFR and c-kit, many of which are overexpressed or constitutively activated in GBM." (PMID 24819299, 2014).
glioblastoma (continued). "It is well known that the classical in vitro conditions (monolayer, medium with 10% serum) do not enable the culturing of many glioblastoma (GB) cells, especially of these with EGFR amplification." (PMID 24498027, 2014). "Additionally, an independent collection of 25 fresh-frozen glioblastomas confirmed lowered pERK levels in G-CIMP+ specimens (p<0.001), indicating suppressed EGFR signaling." (PMID 25277177, 2014). "Going forward, it will be important to determine how LRIG2 ectodomain is released from glioblastoma cells, whether this kind of release is universal, and how LRIG2 ectodomain interact with EGFR and enhance the activation of EGFR." (PMID 25353163, 2014). "We have shown that the response to EGFR inhibitors is not necessarily related to the EGFR levels in glioblastoma cell lines." (PMID 24709958, 2014). "Despite those two studies with positive results, most studies in patients with relapsed glioblastomas treated with EGFR inhibitors obtained negative findings, such as the EORT randomized phase II trial." (PMID 24352766, 2014). "To explore the possible mechanisms underlying the forementioned effects of full-length LRIG2 and LRIG2 ectodomain on the glioblastomas, we examined whether LRIG2 or LRIG2ecto could interact with EGFR." (PMID 25353163, 2014). "Since the published data correlating PTEN and EGFRvIII IHC status to EGFR inhibitor response in glioblastoma patients, there has not been one single study that recapitulated this data." (PMID 24352766, 2014). "We now show that the cardiac glycoside ouabain, an inhibitor of Na,K-ATPase, inhibits EGFR signaling in medulloblastoma cells, but not glioblastoma cells, and prevents EGF-induced cell migration, a prerequisite for an invasive phenotype." (PMID 25052069, 2014). "Drugs that block the activation of these pathways, such as AMPA receptor by antagonist, NBQX, mGluR2/3 inhibitor, LY341495, EGFR inhibitor, Iressa, Akt activation inhibitors Wortmannin and LY294002 have been shown to reduce the growth of glioblastoma when used independently." (PMID 23724064, 2013). "It has been observed that EGFR amplification does not significantly affect the survival of patients with glioblastoma at any age." (PMID 23946790, 2013). "A large number of glioblastomas show EGFR amplification and the combination of Iressa and LY341495 may be suited to block the proliferation of many tumors with EGFR misregulation." (PMID 23724064, 2013). "EGFR and PTEN modulate TF expression through JunD/AP-1 in glioblastoma." (PMID 24086497, 2013). "We also demonstrate that RhoG mediates signaling that is stimulated by cMet and EGFR, two receptors that are deregulated in glioblastoma tumors and that RhoG is overexpressed in human glioblastoma tumor tissue versus non-neoplastic brain." (PMID 22966858, 2012). "We detected EGFR gene amplification in 8 out of the 20 glioblastomas, but not in the other glioma types (p=0.007)." (PMID 22159595, 2012). "Variants of the TERT and RTEL genes are predominantly associated with glioblastoma, whereas variants of the CDKN2A and EGFR genes are associated with overall glioma risk, not with a specific subtype." (PMID 23236348, 2012). "The current drugs that specifically target the tyrosine kinase activity of EGFR or selectively inhibit the mammalian target of rapamycin (mTOR), a PI3K/AKT downstream signal transducer showed little efficacy in treatment of primary glioblastoma." (PMID 22494416, 2012). "One of the most prevalent molecular changes consists of aberrant activation of EGFR, which occur in 50% of glioblastoma, but not seen in low-grade astrocytomas." (PMID 23050879, 2012).
glioblastoma (continued). "Considering the well-documented role for SHP2 in the regulation of EGFR phosphorylation, it is not too surprising that the classical subgroup of glioblastoma, as defined by TCGA, was also the group found to have deregulation of EGFR signalling." (PMID 21934682, 2011). "In a recent study, overexpression of ERRFI1 was shown to decrease proliferation in glioblastoma cells, binding EGFR with STX8, and driving internalized EGFR to late endosomes for degradation, whereas knockdown of ERRFI1 expression resulted in increased tumor invasion." (PMID 21113414, 2010). "As demonstrated by EGFR transcript amplification, by RT-PCR assay, ADF cells and normal brain tissue did not express the EGFRvIII variant that is visible in a grade IV glioblastoma sample used as positive control." (PMID 19196452, 2009). "Among the five glioblastomas with EGFR amplification, immunostaining was negative in four and positive in a scattered pattern in one, in a region displaying some features of oligodendroglial differentiation." (PMID 18492260, 2008). "Accordingly, EGFR amplification has been shown to be a negative prognostic factor for overall survival of glioblastoma patients and to correlate with shorter time to tumour progression." (PMID 17342095, 2007). "Among the growth factor/receptor pathways that are thought to play a role, those involving the epidermal growth factor receptor (EGFR, also known as HER1), the platelet-derived growth factor (PDGF), and the vascular endothelial growth factor (VEGF) are frequently activated in glioblastoma." (PMID 40362634, 2025). "EGFR wild type or EGFR v III EVs may be identified and measured from glioblastoma plasma." (PMID 40840553, 2025). "This retrospective cohort study suggests that the combined molecular profiling of MGMT promoter methylation and EGFR amplification may help to delineate prognostically distinct subgroups within the heterogeneous population of patients with IDH-wild-type glioblastoma (GBM)." (PMID 40722305, 2025). "While EGFR pathway inhibitors might be expected to target oncogene addiction of glioblastoma, attempts to target EGFR with antibodies or small molecules have not been proven to be clinically successful at the moment." (PMID 40075591, 2025). "The glioblastoma antigens currently targeted in the clinic, often in combination, are Cluster of Differentiation proteins (CD133, CD44 & CD70), IL receptors (IL-13Ra2), EGFR and EGFRvIII, ephrin receptor A2 (EphA2), human epidermal growth factor receptor 2 (HER2) and B7-H3." (PMID 41208963, 2025). "However, a randomized phase III trial in newly diagnosed EGFR-amplified glioblastoma found no significant overall survival benefit from adding Depatux-M to standard chemoradiotherapy, and further development of the drug was terminated." (PMID 40918539, 2025). "Relationships between molecular alterations also emerged: notably, EGFR alterations were positively correlated with both CDKN2A/B and PDGFRA alterations in IDH1/2-mutant astrocytoma, reflecting the cooccurrence of canonical glioblastoma molecular alterations in these tumors." (PMID 39164213, 2025). "However, this is not the case for patients presenting with EGFR-mutant glioblastoma, where clinical trials have assessed the efficacy of dacomitinib on extracellular domain variants, as well as other EGFR alterations." (PMID 38548752, 2024). "However, the tumor lacked TERT promoter mutation, EGFR amplification, and polysomy 7/monosomy 10, which are the characteristic genetic alterations of IDH-wild-type glioblastoma in adult patients." (PMID 39335555, 2024).
glioblastoma (continued). "There was 1/77 HGG without enhancement but with positive status of EGFR amplification, thus diagnosed as glioblastomas, IDH-wildtype, while there were 32/45 LGGs with enhancement diagnosed as oligodendrogliomas, IDH-mutant and 1p/19q-deleted (n = 15) and astrocytoma, IDH-mutant (n = 17)." (PMID 38378035, 2024). "GBM, glioblastoma; IDH, Isocitrate Dehydrogenase; EGFR, epidermal growth factor receptor; MGMT, O6-methylguanine-DNA methyltransferase; ATRX, Alpha thalassemia/mental retardation syndrome X-linked; PFS, progression-free survival; OS, overall survival." (PMID 39371551, 2024). "While the presence of EGFRvIII eccDNA may not be entirely implicated in the adaptive selection of EGFR-TKI-resistant tumor cells, EGFRvIII can be rapidly eliminated following TKI administration, thereby increasing resistance in glioblastoma cells." (PMID 39202666, 2024). "Traditional TKIs are not designed to target EGFR in glioblastoma." (PMID 38396993, 2024). "However, these tumors did not exhibit the key molecular alterations of glioblastoma, IDH-wildtype such as TERT promoter mutation, EGFR amplification, or chromosome 7 gain and 10 loss." (PMID 38605367, 2024). "In this review, we will examine the ongoing challenges of glioblastoma treatment and identify immunotherapeutic approaches that could treat glioblastoma, including Isocitrate dehydrogenase (IDH), Epidermal Growth Factor Receptor (EGFR), and Telomerase reverse transcriptase (TERT) peptide vaccines." (PMID 38932383, 2024). "Besides, SH3KBP1(ranked 10th in patient TCGA-BH-A1FD) was reported to serve as a new regulator of carcinogenic EGFR (Epidermal Growth Factor Receptor), and it could also serve as a potential therapy target for GBM (Glioblastoma multiforme, a kind of cancer) patients with EGFR activation." (PMID 38254011, 2024). "Moreover, the EGFR–YTHDF2 axis emerges as a pivotal mechanism that governs the downregulation of LXRA gene expression, playing a crucial role in cholesterol dysregulation within the context of glioblastoma tumorigenesis." (PMID 38398118, 2024). "An anti-EGFR antibody conjugated to MMAF, Depatuxizumab-mafodotin (Depatux-M), was administered to patients with glioblastoma (GBM) receiving standard treatment with radiotherapy plus temozolomide." (PMID 38178200, 2024). "Targeting a tumor-restricted target such as EGFRvIII in glioblastoma via the CAR component drives localization of the cell product to the tumor enabling localized release of a TCE targeting a more homogenously expressed, yet more broadly expressed, second target such as IL13Ra2 or EGFR." (PMID 39606234, 2024). "Not all glioblastoma tumors are EGFR driven and there is much heterogeneity within tumors." (PMID 38396993, 2024). "In summary, dissecting the methylomes of EGFR amplified and non-amplified glioblastomas revealed altered DNA replication, DNA packaging, chromatin silencing and gene silencing pathways, opening potential novel targets and targetable pathways for future precision medicine." (PMID 37444635, 2023). "The epidermal growth factor receptor (EGFR) gene is the most commonly amplified and overexpressed proto‐oncogene in glioblastoma (GBM)." (PMID 35695190, 2023). "In 112 glioblastomas, 49 (44%) were EGFR amplified and 63 (56%) were EGFR not amplified." (PMID 38201434, 2023). "The significance of binding reversibility is also highlighted by the lack of clinical efficacy of the reversible EGFR inhibitors gefitinib, erlotinib, and lapatinib in phase 1–2 trials of patients with glioblastoma, despite sharing similar biochemical features with osimertinib." (PMID 38143440, 2023). "In glioblastoma patients, currently available EGFR inhibitors do not provide a survival benefit but could be used to overcome blood-brain barrier ABCB1/ABCG2-mediated drug resistance via transporter internalization/degradation." (PMID 36973040, 2023).